KRAS (KRas proto-oncogene, GTPase)
Diseases named in the same sentence as KRAS in open-access papers (continued):
Sharing a sentence is not in itself a finding about the gene and the disease.
colorectal cancer (continued). "The KRAS in-colorectal-cancer collaborative group (RASCAL II) study has shown that a glycine to valine mutation on codon 12 of the KRAS gene is aggressive in patients with Duke's C CRC." (PMID 24212777, 2011). "In practice, it is considered that EGFR-positive as well as KRAS wild-type colorectal cancer patients have satisfied criteria for cetuximab therapy." (PMID 21554739, 2011). "In colorectal cancers the incidence of KRAS or BRAF mutations are about 50% of patients (roughly 40% KRAS and 10% BRAF mutations) and was a found to be associated with poor prognosis in colorectal cancer." (PMID 24212832, 2011). "Consistent with earlier reports, our results show that KRAS and BRAF mutation frequencies in colorectal cancer were 44.3% and 13.0%, respectively, while EGFR mutations were detected in 11.1% of the lung cancer specimens." (PMID 21943394, 2011). "The potential predictive and prognostic biomarkers which have stemmed from the study of the genetic basis of colorectal cancer and therapeutics are discussed with a focus on mismatch repair status, KRAS, BRAF, 18qLOH, CIMP and TGF-β." (PMID 24212777, 2011). "As approaches to CIMP characterization in colorectal cancer continue to evolve, it is clear that BRAF and KRAS oncogene mutations will continue to refine any definition of CIMP." (PMID 21559209, 2011). "Activating mutation of KRAS and BRAF are focused on as potential prognostic and predictive biomarkers in patients with colorectal cancer (CRC) treated with anti-EGFR therapies." (PMID 21285991, 2011). "Although limited numbers of patients have been tested, it seems that activating mutations in the KRAS oncogene are observed in approximately 40% of SBA patients, which is similar to the rate observed in colorectal cancer." (PMID 19935793, 2010). "The given percentage of KRAS mutation in NSCLC is 21–43% and 33% for colorectal cancer and for pancreatic carcinomas 75–82.4%." (PMID 21197450, 2010). "We compared the COLD-PCR melting curve assay to regular PCR melting analysis in a cohort of 61 FFPE colorectal cancer specimens which included 14 blinded samples that had KRAS testing done previously at outside institutions." (PMID 21110880, 2010). "Recent studies aimed at comprehensive sequencing of genes mutated in colorectal cancer confirmed that APC and KRAS mutations are among the most common mutations found in colorectal cancer." (PMID 20298593, 2010). "KRAS, BRAF/KRAS, and LKB/KRAS mutation(s) are correlated with sensitivity to MEK inhibitors in ovarian cancer, colorectal cancer, and NSCLC, respectively." (PMID 21124782, 2010). "We selected 21 colorectal cancer cell lines, characterized their DNA methylation profiles, and determined their BRAF and KRAS mutation status." (PMID 20027224, 2009). "KRAS and treatment response to Cetuximab or Panitumumab in previously treatment patients with colorectal cancer." (PMID 19386128, 2009). "KRAS and treatment response to Cetuximab-containing regiments in chemotherapy-naïve patients with colorectal carcinoma." (PMID 19386128, 2009). "In order to understand the importance of KRAS, PIK3CA and BRAF mutations for the progression of the various types of colorectal cancer, we compared the frequency of these oncogenic events in the series of polyps and in 50 MSI and 53 MSS CRC." (PMID 18782444, 2008). "Using a microsatellite stable (MSS) colorectal cancer (CRC) cell line (Colo741) having mutated BRAF and KRASWT, we also aimed to investigate the KRAS-BRAF interaction." (PMID 19087308, 2008).
colorectal cancer (continued). "By analyzing a large cohort of colorectal cancer patients routinely tested for KRAS, the authors assessed whether KRAS‐G12C detection could serve as a pre‐screening tool for the syndrome." (PMID 41347765, 2026). "Similarly, the TLR9 agonist IMO has demonstrated the ability to synergize with cetuximab in KRAS mutant colorectal cancer models, highlighting the interconnectedness of these pathways." (PMID 41550766, 2026). "To investigate the effects of different KRAS G12 mutants, we first characterised the SW48 isogenic colorectal cancer cell line harbouring heterozygous mutations in KRAS at codon 12 (SW48+/+, SW48+/G12A, SW48+/G12C, SW48+/G12D, SW48+/G12V, hereafter also referred to as WT, G12A/C/D/V)." (PMID 41266617, 2026). "This suggests that the reliance on the glutamine-glutamate cycle might be a common feature of KRAS mutant cells in different colorectal cancer contexts." (PMID 41266617, 2026). "This process is essential to prevent 8‐oxoG‐induced mutagenesis, a common oxidative DNA lesion that, if unrepaired, may cause G:C > T:A transversion mutations in colorectal cancer driver genes, such as APC and KRAS, and contribute to carcinogenesis." (PMID 41347765, 2026). "Consequently, we propose a highly sensitive strategy to enhance the therapeutic targeting of oncogenic KRAS in living colorectal cancer cells." (PMID 40949096, 2025). "KRAS mutations are implicated in approximately 23% of all human malignancies, with particularly high prevalence in pancreatic ductal adenocarcinoma (PDAC) (~92%), colorectal cancer (CRC) (~49%), and non-small cell lung cancer (NSCLC) (~35%)." (PMID 41294676, 2025). "These targeted agents have received FDA approval for treating KRAS G12C–mutated non–small cell lung cancer (NSCLC) and colorectal cancer (CRC), with sotorasib approved in May 2021 and adagrasib following in December 2022." (PMID 41355935, 2025). "Seventeen colorectal cancers harboring a V600E mutation also presented with additional, predicted pathogenic mutations in KRAS, NRAS, or NF1 (17/709, 2.40%), comprising 13 colorectal cancers with NF1-inactivating mutations and four with KRAS mutations (4/709, 0.71%, mostly G12D)." (PMID 39751654, 2025). "A systematic review concluded that in patients with mutant KRAS colorectal cancer, plasma KRAS‐positive status may be a poor prognostic factor for overall survival, progression‐free survival, and disease‐free survival." (PMID 40698441, 2025). "As a result, the use of MEK inhibitors in conjunction with PI3K, AKT, or mammalian target of rapamycin (mTOR) inhibitors has not led to desirable outcomes in the treatment of KRAS-mutated colorectal cancer in clinical settings." (PMID 40519270, 2025). "Other miRNAs involved in the regulation of RAS family members include miR-18a-3p and miR-143 in colorectal cancer, as well as miR-217, which directly interacts with KRAS mRNA by binding to the 3’-untranslated region, leading to its degradation or inhibition of translation." (PMID 39858030, 2025). "A total of 3795 patients were included in the analysis, of which 982 had colorectal cancer with 421 KRAS‐positive cases and 36 NRAS‐positive cases, 1246 had breast cancer with 410 PIK3CA‐positive cases, and 1567 had non‐small cell lung cancer with 300 EGFR‐positive cases." (PMID 40056420, 2025). "Compared to existing molecular tools for colorectal cancer staging—such as APC, KRAS, BRAF, NRAS and PIK3CA mutations—our study offers a novel transcriptomic perspective by identifying stage-specific gene expression signatures that distinguish adenoma, CIS and adenocarcinoma." (PMID 40362431, 2025).
colorectal cancer (continued). "KRAS mutations are associated with treatment and prognostic outcomes in colorectal cancer patients.There have been no studies on utilizing the peritumoral images to predict KRAS mutation status in rectal cancer patients." (PMID 40653800, 2025). "Additionally, the combination of WNT974 and artesunate (ART) has shown capability in vivo activity by degrading KRAS protein, one of the most challenging oncogenic drivers in colorectal cancer treatment in animals." (PMID 41149466, 2025). "In a preclinical study in colorectal cancer cells with or without KRAS and PIK3CA mutations, the combination of ribociclib with alpelisib was more effective than each drug alone in vitro and in vivo in mice xenografts." (PMID 40699853, 2025). "Moreover, high tumor EREG expression predicts a favorable response to cetuximab in KRAS wild-type colorectal cancer, suggesting its utility as a companion biomarker." (PMID 41175573, 2025). "Furthermore, PLK1 showed a synthetic lethal interaction with the KRAS function in colorectal cancer cells based on genome-wide RNAi screen." (PMID 41458961, 2025). "KRAS, NRAS, and HRAS are the three main isoforms affected in cancer; among them, KRAS is the most frequent gain-of-function mutation, occurring in up to 90% of pancreatic cancer, 50% of colorectal cancer, and 30% of lung adenocarcinoma." (PMID 40970755, 2025). "Our study is important in that it draws attention to the prognostic importance of KRAS mutation in early-stage colorectal cancer (an area of controversy and lack of data)." (PMID 40142219, 2025). "Future work should explore the function and immunomodulatory effects of C9ORF50 in KRAS‐mutant colorectal cancer models to determine whether its role remains conserved across different genetic backgrounds." (PMID 41472851, 2025). "Of the 335 colorectal cancers, 13 (3.88%) with atypical KRAS also carried a typical KRAS mutation, and none of those tumors had an additional BRAF, NRAS, or NF1 mutation." (PMID 39751654, 2025). "Of 335 colorectal cancers harboring atypical KRAS mutations in the combined cohorts, 317 (94.6%) had no concomitant pathogenic BRAF mutation, with BRAF mutations in the remaining 18 all belonging to class 3 (18/335, 5.4%)." (PMID 39751654, 2025). "Traditional chemotherapy could be used for KRAS-mutant colorectal cancer; however, it was less effective than in KRAS wild-type cases." (PMID 40611261, 2025). "While KRAS/NRAS mutations are well known to predict a lack of efficacy from anti-EGFR antibodies in colorectal cancers, studies investigating the addition of the EGFR TKI erlotinib to chemotherapy in advanced BTC and PDA suggested a similar pattern." (PMID 40507311, 2025). "Mutant KRAS halts calcium influx by remodeling STIM expression in colorectal cancer cells." (PMID 40779492, 2025).
colorectal cancer (continued). "KRAS mutations are especially prevalent in pancreatic ductal adenocarcinoma (PDAC), colorectal cancer (CRC, ~40%), and non-small cell lung cancer (NSCLC, ~30%), with PDAC showing over 90% prevalence of KRAS mutations, predominantly at codon G12 (G12D, G12V, G12R)." (PMID 41471277, 2025). "Moreover, preclinical and clinical data suggest that PLK1 inhibition is effective in KRAS-mutant colorectal cancer, providing a rationale for more investigation on the combination efficacy with KRASG12C inhibition." (PMID 39807828, 2025). "Given that mutations in APC, KRAS, and BRAF are among the most frequently occurring genetic alterations in colorectal cancer, our findings suggest that the Prkci–c-Myc axis may represent a generalizable and mutation-independent oncogenic mechanism in CRC." (PMID 41188443, 2025). "In the context of colorectal cancer, this mechanism provides an alternative pathway for driving tumorigenesis in cases lacking canonical KRAS, NRAS, or BRAF mutations." (PMID 40868090, 2025). "In addition to KRAS, mutations in BRAF also play an important role in colorectal cancer, although they are less common compared to KRAS mutations." (PMID 40083375, 2025). "Determining the mutational status of KRAS is essential before initiating treatment plans for cancers such as non-small cell lung cancer (NSCLC) and colorectal cancer (CRC), particularly when considering therapies targeting the epidermal growth factor receptor (EGFR)." (PMID 41294676, 2025). "The results suggest that standard first-line therapies (immunotherapy plus chemotherapy) and colorectal cancer regimens may have a relatively limited impact on survival in KRAS-driver positive advanced PEAC." (PMID 39917173, 2025). "However, the mutation rates of KRAS and BRAF in colorectal cancer patients are only 40% and 10%, respectively." (PMID 40547026, 2025). "Finding an effective treatment for KRAS mutant colorectal cancer is of high priority." (PMID 40526688, 2025). "A previous work on Fragaria x ananassa showed cell cycle arrest in G2/M together with an anticancer proapoptotic effect of nonextractable strawberry polyphenols on KRAS mutated colorectal cancer HCT116 cells." (PMID 40207736, 2025). "Despite decades of research, there are still no effective targeted treatments for the nearly 45% of colorectal cancer (CRC) patients harboring a mutation in their KRAS gene." (PMID 40864819, 2025). "In colorectal cancer, Lu/BCAM is overexpressed in clinical KRAS-mutant hepatic metastasis and the inhibition of its interaction with laminin α5 impaired adhesion of colorectal cancer cells to vascular endothelial cells, resulting in a reduction of metastatic growth." (PMID 40332051, 2025). "The KEYNOTE177 trial reported that pembrolizumab was less effective in patients with MSI-H colorectal cancer who had KRAS mutations, a strong driver gene, than in those without mutations." (PMID 40032770, 2025). "This study focuses on colorectal cancer patients and employs multivariate analysis to elucidate the specificity and sensitivity of common diagnostic methods, including FIT, KRAS mutation, M3 and Methylation, thereby providing a reference for clinical screening and diagnosis of colorectal cancer." (PMID 40771811, 2025). "In KRAS-mutant colorectal cancer, the addition of ferroptosis inducers to cetuximab (an anti-EGFR monoclonal antibody) overcomes the limited efficacy of cetuximab-based chemotherapy imposed by KRAS mutation, effectively suppressing tumor growth and lymph node metastasis." (PMID 41479924, 2025). "Adapting from established methods for snRNP in vitro reconstitution for structural biology studies, we reconstituted a modified Sm protein‐siRNA ribonucleoprotein complex (SmiRNP‐EGF‐H5E) that can effectively deliver siRNA into HCT116 colorectal carcinoma cells to silence the KRAS gene." (PMID 40702844, 2025).
colorectal cancer (continued). "KRAS mutation (KRAS*)—the key driver mutation in pancreatic ductal adenocarcinoma (PDAC) and non-small cell lung cancer (NSCL)—also plays a secondary role in colorectal carcinoma (CRC) progression." (PMID 40750884, 2025). "Moreover, analysis of human colorectal carcinoma datasets obtained from TCGA revealed a positive correlation between REGγ expression and KRAS expression." (PMID 40091835, 2025). "This confirms previous literature that SMARCA4 uniquely acts as a tumor promoter in colorectal cancer, and may present a new role of SMARCA4 in tumorigenesis in CRC with a KRAS mutation." (PMID 38446332, 2024). "The expression of SIGLEC9 was significantly elevated in colorectal cancer tissues, independent of mutations in the KRAS, NRAS, BRAF, PIK3CA, and AKT genes, as well as MSI status." (PMID 39727942, 2024). "In economic evaluations of colorectal cancer treatment, a study from Japan assessed the cost-effectiveness of optimal treatment regimens for patients with KRAS wild-type metastatic colorectal cancer using FOLFIRI in combination with bevacizumab (Bmab), cetuximab (Cmab), or panitumumab (Pmab)." (PMID 39606076, 2024). "Similarly, osthole decreases AMPK phosphorylation and exactly promotes ferroptosis in KRAS-mutant colorectal cancer cells." (PMID 38738174, 2024). "Oncogenic KRAS is responsible for driving invasion and maintaining metastases in colorectal cancer." (PMID 38338768, 2024). "STAT3 and KRAS were significantly down-regulated in colorectal cancer." (PMID 39830506, 2024). "In addition, a study has shown that the amino acid transporter SLC7A5 is essential for the effective growth of KRAS mutant colorectal cancer." (PMID 39588377, 2024). "While genes like KRAS, APC, and PIK3CA maintain mutation frequencies relatively consistent with MSS colorectal cancer, the most significant observation is the markedly higher mutation frequency of DNA mismatch repair (MMR)‐related genes in MSI‐H colorectal cancer compared to MSS colorectal cancer." (PMID 38746969, 2024). "However, neither of these compounds was approved as single agents against colorectal cancer or other types of cancer with KRAS G12C due to subpar objective response rates." (PMID 38668053, 2024). "Over 77% of all pancreatic cancer patients were shown to have KRAS mutations, 42% of colorectal cancer cases have KRAS mutations, and approximately 30% of Non-Small Cell Lung Cancer (NSCLC) cases have KRAS mutations." (PMID 39372214, 2024). "The sole study in colorectal cancer that established an association between KRAS mutation and DPYD variations demonstrated that the -c.496A>C DPYD variant is exclusively present in patients with wild-type KRAS." (PMID 38248103, 2024). "In a phase 1 trial, a lymph node-targeting mutant KRAS peptide vaccine combined with CpG adjuvant is safe, reduces expression of tumor biomarkers and elicits mutant KRAS-specific T cells in patients with pancreatic cancer and colorectal cancer." (PMID 38195752, 2024). "Notably, a study of the use of EGFR inhibitors in colorectal cancer tumors with mutations and sotorasib resistance found that upregulation of EGFR was a common resistance mechanism, and dual targeting of EGFR and KRAS blocked acquisition of resistance." (PMID 38639476, 2024). "To decide the antitumor activity of RGD-p21Ras-scFv in nude mice, we selected the KRAS wild-type colorectal cancer cell line HT29 and the KRASG12V mutant colorectal cancer cell line SW480 with low IC50 values to establish nude mouse xenograft model and administered the drug for treatment." (PMID 38216883, 2024). "Previous studies have provided results, not on LSCC, but on the role of KRAS polymorphisms, such as rs8720, and its role in increasing the risk of other cancers, including colorectal cancer." (PMID 39867023, 2024). "Furthermore, in this study, we observed that, in KRAS, this miRNA targets the rs8720 locus, an SNV that has previously been associated with colorectal cancer." (PMID 39057123, 2024).